BGN (biglycan)
Description:
May be involved in collagen fiber assembly.
Synonyms: SLRR1A; DSPG1; MRLS; PG-S1; PGI; SEMDX
Tractability: Antibody: its Gene Ontology location is reachable by antibodies, with high confidence; UniProt places it where antibodies can reach, with medium confidence; UniProt predicts a signal peptide or a membrane-spanning region. PROTAC: its protein half-life has been measured.
Gene: Protein-coding gene on chromosome X (153,488,654 to 153,510,299, forward strand). Ensembl gene ENSG00000182492.
Subcellular location: Secreted, extracellular space, extracellular matrix
Subcellular location (Human Protein Atlas): Golgi apparatus; Endoplasmic reticulum; Predicted to be secreted
Pathways (Reactome):
Disease: Defective B3GALT6 causes EDSP2 and SEMDJL1; Defective B3GAT3 causes JDSSDHD; Defective B4GALT7 causes EDS, progeroid type; Defective CHST14 causes EDS, musculocontractural type; Defective CHST3 causes SEDCJD; Defective CHSY1 causes TPBS
Metabolism: CS-GAG biosynthesis; CS/DS degradation; DS-GAG biosynthesis; Glycosaminoglycan-protein linkage region biosynthesis
Extracellular matrix organization: ECM proteoglycans
Gene Ontology:
Molecular function: protein binding; extracellular matrix structural constituent; extracellular matrix structural constituent conferring compression resistance; cytokine binding; extracellular matrix binding; glycosaminoglycan binding
Biological process: blood vessel remodeling
Cellular component: cell surface; extracellular exosome; extracellular matrix; extracellular region; transport vesicle; elastic fiber; gel phase of interstitial matrix; Golgi lumen; lysosomal lumen; sarcolemma
Gene-disease validity (ClinGen):
ClinGen rates the evidence that BGN causes each of these diseases.
Meester-Loeys syndrome (X-linked): Strong.
familial thoracic aortic aneurysm and aortic dissection (autosomal dominant): Limited. A rare genetic vascular disease characterized by the familial occurrence of thoracic aortic aneurysm, dissection or dilatation affecting one or more aortic segments (aortic root, ascending aorta, arch or descending aorta) in the absence of any other associated disease.
Homologues: Orthologues: chimpanzee BGN (99% identical), macaque BGN (99% identical), mouse Bgn (96% identical), rat Bgn (96% identical), dog BGN (95% identical), guinea pig BGN (95% identical), pig BGN (94% identical), rabbit BGN (94% identical), tropical clawed frog bgn (77% identical), zebrafish bgnb (70% identical), zebrafish bgna (67% identical). Paralogues in human: ASPN (54% identical), DCN (54% identical), LRRTM4 (25% identical), PODN (24% identical), FLRT1 (24% identical), FLRT2 (24% identical), FLRT3 (24% identical), PODNL1 (23% identical), LRRC4C (23% identical), LRRC4 (22% identical), LRRC4B (22% identical), LRRTM3 (22% identical), and 10 more.
Diseases named in the same sentence as BGN in open-access papers:
BGN is named in the same sentence as 165 diseases in open-access papers, as found by Europe PMC text mining. Sharing a sentence is not in itself a finding about the gene and the disease. The quoted sentences say what the papers report.
gastric cancer (50 papers, 2010 to 2025). A primary or metastatic malignant neoplasm involving the stomach. "We identified several genes, including FN1, COL1A2, THBS2, COL3A1, COL5A1, and BGN, which appear to be associated with poorer outcomes for stomach cancer patients." (PMID 38610959, 2024). "BGN was overexpressed in pancreatic cancer and inhibited cell development by blocking mitotic G1 phase of pancreatic cancer cells, while BGN was overexpressed in gastric cancer and positively linked with tumor cell repair, invasion, and migration." (PMID 38396140, 2024). "High expression of BGN in gastric cancer tissues was associated with lymph node metastasis by activation of the FAK signaling pathway." (PMID 35053617, 2022). "A previous study has shown that BGN promotes tumor invasion and metastasis in gastric cancer both in vitro and in vivo and is associated with TNM stage." (PMID 36110576, 2022). "Biglycan (BGN) was found to be associated with tumor progression in gastric cancer, pancreatic adenocarcinoma, endometrial cancer, and prostate cancer." (PMID 36523769, 2022). "Kaplan-Meier analysis showed that higher expression of BGN was significantly associated with poorer RFS in gastric cancer patients." (PMID 36110576, 2022). "In the context of gastric cancer, significantly increased tissue biglycan levels have been linked to lymph node metastasis and depth of tumor invasion, both in vivo and in vitro." (PMID 34917515, 2021). "For example, in gastric cancer and colorectal cancer, mRNA and protein levels of BGN isolated from tumor tissues were associated with tumor progression and malignancy." (PMID 33709550, 2021). "BGN expression is significantly higher in gastric cancer tissues and associated with lymph node metastasis, depth of tumor invasion and TNM stage." (PMID 24681892, 2014). "For example, BGN expression was associated with the progression of colorectal cancer, gastric cancer and pancreatic adenocarcinoma." (PMID 24223213, 2013). "Overexpression of BGN at mRNA and/or protein level has been associated with advanced tumor stages, metastases development, drug resistance, and poor prognosis in patients with ovarian, prostate, oral, colon, and gastric cancers." (PMID 39762990, 2025). "BGN is highly expressed in multiple tumors, including pancreatic cancer, esophageal cancer, gastric cancer, colon cancer, endometrial cancer and prostate cancer, and transcriptional analysis also revealed that BGN is a promising diagnostic and therapeutic target in different cancers." (PMID 39578715, 2024). "Several studies have demonstrated a close association between the BGN gene and inflammation, with its overexpression observed in tumor tissues such as human pancreatic cancer and gastric cancer, where it plays crucial roles in tumor growth, adhesion, and invasion." (PMID 38654221, 2024). "GSEA results suggested that BGN was significantly enriched in gene signatures related to metastasis and poor prognosis, revealing that BGN might be associated with cell proliferation, poor differentiation, and high invasiveness of gastric cancer." (PMID 36110576, 2022). "GSEA results suggested that BGN was significantly enriched in gene signatures related to metastasis and poor prognosis, revealing that BGN might be associated with proliferation, poor differentiation, and high invasiveness of gastric cancer." (PMID 36110576, 2022). "BGN is further highly expressed in gastric cancer and has been associated with poor prognosis." (PMID 36358747, 2022). "It was found that expression of BGN (HR 1.9 [1.56–2.32], P = 1.3 × 10–10) was associated with worse overall survival (OS) for gastric cancer patients, as well as MMP2 (HR 1.78 [1.47–2.16], P = 2.6 × 10–9), COL1A1 (HR 1.49 [1.22–1.81], P = 8.2 × 10–5) and FN1 (HR 1.46 1.23–1.74], P = 1.3 × 10–5)." (PMID 29050278, 2017).
gastric cancer (continued). "This study elucidates the mechanism by which GLIS Family Zinc Finger 2 (GLIS2) promotes epithelial-mesenchymal transition (EMT) in gastric cancer through biglycan (BGN) activation and Wnt/β-catenin stimulation." (PMID 40936440, 2025). "It has been reported by different authors that BGN protein expression in gastric cancer was mainly located in the cytoplasm of epithelial cells." (PMID 36972253, 2023). "The mechanism of BGN-induced gastric cancer involves the induction of epithelial to mesenchymal transition (EMT) and upregulation of chromatin reprogramming factors." (PMID 38041130, 2023). "BGN has been shown to regulate various signaling pathways in tissue specific cancers such as p38 signaling in colon cancer, NFκB signaling in gastric cancer and PI3K-Akt-NFκB signaling axis in retinoblastomas." (PMID 35053617, 2022). "Kaplan-Meier analysis of BGN for the RFS revealed that higher BGN expression level portended poorer prognosis in gastric cancer patients (p = 0.03)." (PMID 36110576, 2022). "In this study, we investigated the prognostic value of BGN in gastric cancer by involving an external transcriptome data set from the TCGA database." (PMID 36110576, 2022). "The purpose of the present study is to verify the BGN expression and the prognostic value of BGN in gastric cancer." (PMID 36110576, 2022). "In order to further understand the carcinogenic mechanism, it is essential to explore the upstream regulation of BGN in gastric cancer." (PMID 36110576, 2022). "For gastric cancer, the mRNA expression level of BGN in tumor tissue was significantly higher than that in normal tissue." (PMID 36110576, 2022). "By knocking out BGN in gastric cancer cells, decreased levels of mesenchymal markers N-cadherin, ZEB1, ZEB2, Snail, NANOG, DPP4, and 3/4 October (POU5F1), and increased expression of the epithelial marker E-cadherin are observed." (PMID 36358747, 2022). "Kaplan-Meier analysis revealed that overexpression of BGN was significantly associated with poorer RFS in a dose-dependent manner in both stage I-III and stage IV gastric cancer patients." (PMID 36110576, 2022). "High expression of BGN mRNA was significantly related to poor prognosis, which suggested that BGN was a potential prognostic biomarker and therapeutic target of gastric cancer." (PMID 36110576, 2022). "For gastric cancer, the protein expression level of BGN in tumor tissue was significantly higher than that in normal tissue." (PMID 36110576, 2022). "To understand the role of BGN in gastric cancer, we analyzed our tissue microarray, including 125 cases of gastric cancers, for immunohistochemical BGN expression." (PMID 36110576, 2022). "Other studies have been performed on BGN and gastric cancer, most notably in bioinformatics analysis; they have related gastric cancer patients with healthy individuals." (PMID 34054953, 2021). "Biglycan was able to modulate gastric cancer aggressive features as cell survival, migration, and angiogenesis." (PMID 33809543, 2021). "With integrated bioinformatics analysis, BGN, LOX, MMP-9, SERPINE1, and TGFB1 proteins have been selected as suitable diagnostic biomarkers for noninvasive to invasive stages of gastric cancer." (PMID 34054953, 2021). "In gastric cancer tissues where protein expression was detected, the levels of the protein (BGN, VCAN, COL1A1 and TIMP1) were higher than in normal tissues." (PMID 34356118, 2021). "BGN expression is increased in many cancers including bladder cancer, colorectal cancer, gastric cancer, esophageal cancer, prostate cancer, and endometrial cancer and various factors modulate its expression, including p38, HIF-1, TGF-β/Smad4, and NF-κB." (PMID 32050430, 2020). "It has been reported that biglycan is overexpressed in various cancers and correlates with progression, metastasis, and angiogenesis of gastric cancer, endometrial cancer, prostate cancer, and bladder cancer." (PMID 32821344, 2020).
gastric cancer (continued). "On a positive note, for the first time, we found that celastrol inhibited the expression of BGN, and over-expression of BGN prevented celastrol-induced necroptosis in gastric cancer cells." (PMID 31739592, 2019). "Recently, several research groups have found abnormal expression of BGN in tumors, which is closely related to the migration and poor prognosis of tumors, including gastric cancer." (PMID 31739592, 2019). "High expression of BGN was existed in gastric cancer cells, which was down-regulated by celastrol in a dose dependent manner." (PMID 31739592, 2019). "This study unveils the mechanism of celastrol-induced gastric cancer cell death and underscores the importance of BGN-mediated necroptosis and inflammation in celastrol-induced cell death." (PMID 31739592, 2019). "In this study, for the first time, our results indicate the celastrol induced necroptosis and attenuated the release of pro-inflammatory cytokines via down-regulating BGN level in the gastric carcinoma cell lines HGC-27 and AGS cells." (PMID 31739592, 2019). "Biglycan (BGN) is expressed in the ECM, and its upregulation was associated with several types of cancer, including colon tumor, pancreatic cancer and gastric cancer." (PMID 29484116, 2018). "Four hub genes with worse overall survival (OS) of gastric cancer patients were detected and the Kaplan Meier-plotter was applied to visualize them, including BGN, MMP2, COL1A1 and FN1." (PMID 29050278, 2017). "These in vivo data were consistent with the in vitro results and confirmed that BGN overexpression promotes gastric cancer metastasis." (PMID 24681892, 2014). "In this study, we first analyzed expression of BGN in gastric cancer tissues using qRT-PCR and immunohistochemistry." (PMID 24681892, 2014). "In addition to the classical angiogenesis signals, studies revealed other potential pro-angiogenic targets based on cancer types, such as DGKG in HCC, BGN in gastric cancer and AEBP1 in CRC." (PMID 40248695, 2025). "Furthermore, gastric cancer cells overexpress Biglycan (BGN), which stimulates VEGF expression through the interaction between NF-κB and HIF-α." (PMID 40248695, 2025). "BGN has also been reported to promote EMT via the NF-κB pathway in gastric cancer." (PMID 39578715, 2024). "BGN protein level in gastric cancer tissue was determined by immunohistochemistry (IHC)." (PMID 36110576, 2022). "Here, the prognostic significance of BGN was evaluated in gastric cancer." (PMID 36110576, 2022). "Therefore, the BGN expression level was negatively correlated with the prognosis of gastric cancer patients in a dose-dependent manner." (PMID 36110576, 2022). "In gastric cancer tissue samples, the signal of BGN protein could only be seen in the extracellular matrix rather than in the intracellular matrix, which made it difficult for quantification." (PMID 36110576, 2022). "BGN plays an oncogenic role by activating the FAK signaling pathway in gastric cancer." (PMID 36110576, 2022). "BGN mRNA levels were negatively correlated with RFS of gastric cancer patients." (PMID 36110576, 2022). "Cancer metastasis was observed with overexpression of BGN in gastric cancer tissues." (PMID 35053617, 2022). "Likewise, biglycan was also associated with in vitro tubular angiogenesis by activating the TLR signaling pathway and inducing VEGF expression in colon and gastric cancer." (PMID 33809543, 2021). "In line with this, biglycan was recently shown to modulate gastric cancer aggressive features as cell survival, migration, and angiogenesis and biglycan knockout gastric cancer cells showed increased levels of PARP1 (Poly [ADP-ribose] polymerase 1) and Caspase 3 cleavage." (PMID 34917515, 2021). "Correlations of biglycan expression with aggressive clinicopathological features and poor survival in human cancers such as pancreatic adenocarcinoma, colorectal cancer, and gastric cancer have been reported." (PMID 32984024, 2020).
gastric cancer (continued). "BGN promotes tumor invasion and metastasis of gastric cancer both in vitro and in vivo." (PMID 31992202, 2020). "In conclusion, our study for the first time found that celastrol could decrease the expression of BGN to induce necroptosis and ameliorate inflammation in gastric cancer cells." (PMID 31739592, 2019). "Recent studies have indicated significantly higher expression of BGN in tumor tissues compared with adjacent normal tissues, including colon tumor, ovary cancer, pancreatic adenocarcinoma, intrahepatic cholangiocarcinoma, and gastric cancer." (PMID 31739592, 2019). "We then sought to investigate whether celastrol mediated inflammation by targeting BGN in gastric cancer cells; we evaluated the secretion of pro-inflammatory cytokine TNF-α and IL-8." (PMID 31739592, 2019). "Despite emerging insight that BGN may affect cancer development dependent on inflammation, the relation between BGN and necroptosis in gastric cancer remains to be uncovered." (PMID 31739592, 2019). "BGN expression was upregulated in gastric cancer tissues to enhance gastric cancer invasion." (PMID 31739592, 2019). "In conclusion, this bioinformatics analysis demonstrated that DEGs and hub genes, such as BGN, might promote the development of gastric cancer, especially in tumor metastasis." (PMID 29050278, 2017). "BGN also promotes tumor invasion and metastasis of gastric cancer both in vitro and in vivo." (PMID 28424419, 2017). "In the present study, we investigated the role of BGN in gastric cancer metastasis, in vitro and in vivo.Speed of wound healing was significantly increased in BGN-transfected gastric cells and significantly decreased after transfecting with BGN shRNA." (PMID 24681892, 2014). "Moreover, BGN overexpression promoted migration and invasion of gastric cancer cells in vitro and in transplanted tumor models." (PMID 24681892, 2014). "In conclusion, we found that BGN expression in gastric cancer tissues was significantly upregulated compared with its adjacent normal gastric tissues, and was correlated with the clinical features of axillary lymph node metastasis, depth of tumor invasion and TNM stage." (PMID 24681892, 2014). "BGN was up-regulated in 77.8% (95/122) of gastric cancer patients." (PMID 24681892, 2014). "Thus, we investigated gene signatures that are associated with the presence or absence of BGN expression in 408 stomach cancers from the TCGA dataset." (PMID 33809543, 2021). "Furthermore, celastrol activated receptor-interacting protein 1 and 3 (RIP1 and RIP3) and subsequently promoted the translation of mixed-lineage kinase domain-like (MLKL) from cytoplasm to plasma membrane, leading to necroptosis of gastric cancer cell, which was blocked by over-expression BGN." (PMID 31739592, 2019). "Similarly, gastric cancer (GC)-derived exosomal BGN is internalized by macrophages, where it interacts with NONO protein to drive pro-tumoral polarization and CXCL10 upregulation." (PMID 41417432, 2025). "BGN has been reported to exert antiapoptotic effect in HCT116 colon cancer cells and to promote the proliferation of gastric cancer cells, suggesting a potential oncogenic role in certain gastrointestinal malignancies." (PMID 38786104, 2024). "Therefore, BGN may be a potential prognostic and therapeutic biomarker for gastric cancer." (PMID 36110576, 2022). "The HRs were 1.44 (95% CI 1.02-2.06, p = 0.038) and 2.16 (95% CI 1.22-3.87, p = 0.007) for high BGN expression in stages I-III (n = 365) and stage IV gastric cancer patients, respectively." (PMID 36110576, 2022). "The expression of BGN, LOX, MMP-9, SERPINE1, and TGFB1 proteins was significantly higher in the samples of gastric cancer patients compared to the healthy people." (PMID 34054953, 2021). "In accordance with our results, several other studies have shown that BGN expression is increased in various cancers including, CRC, gastric cancer, esophageal cancer, and prostate cancer." (PMID 34590603, 2021).